CD63 (CD63 molecule)
Diseases named in the same sentence as CD63 in open-access papers (continued):
Sharing a sentence is not in itself a finding about the gene and the disease.
periodontitis (6 papers, 2018 to 2026). An acute or chronic inflammatory process that affects the tissues that surround and support the teeth. "Our analysis has shown that CAL and salivary CD63 levels were correlated in patients with periodontitis." (PMID 38813360, 2024). "We found a significant elevation in salivary levels of CD63 in the periodontitis and gingivitis groups compared to healthy controls, and a significant increase in CD63 levels in the periodontitis group compared to the gingivitis group." (PMID 38813360, 2024). "Compared to healthy/gingivitis subjects, the total concentration of EV in gingival crevicular fluid (GCF) increased in periodontitis patients, and the CD63 exosome markers in GCF increased in periodontitis patients." (PMID 38129853, 2023). "The expression of CD11b, CD63, and CD66b on the cPMNs was low and comparable in healthy controls and in periodontitis patients (p > 0.05, respectively)." (PMID 30143044, 2018). "Azurocidin and CD63 levels were significantly higher in patients with periodontitis and patients with gingivitis than in controls (P < 0.05), and significantly higher in patients with periodontitis than in patients with gingivitis (P < 0.05)." (PMID 38813360, 2024). "Additionally, the upregulated expression of CD11b and the tendency for increased CD63 in periodontitis patients’ oPMNs, suggest a higher release of granular content, possibly related to activation during the migration through the inflamed periodontal tissues and along the subgingival biofilm." (PMID 30143044, 2018). "In intergroup comparisons of CD63 levels across all pairs of groups, there was a substantial difference between each group and the others, but there was only one significant correlation, between CD63 and CAL in the periodontitis group." (PMID 38813360, 2024). "CD63+ exosomes in GCF were increased in patients with periodontitis compared with those without periodontitis." (PMID 37114060, 2023). "A recent report demonstrated salivary CD9+ and CD 81+ sEVs were decreased in periodontitis patients, while another report showed that salivary CD63+ sEVs are comparable in periodontitis and non-periodontitis patients." (PMID 33670900, 2021).
ischemic stroke (5 papers, 2013 to 2025). A stroke disorder caused by obstruction of blood flow to the brain, due to thrombotic (local blood clot formation) or embolic (due to a blood clot or other material traveling from another site) event. "Among the many neurovascular factors secreted by mesenchymal stem cells, CD63-expressing exosomes present in lysosomal membranes exert platelet activity; in ischemic stroke they promote platelet hyperactivation." (PMID 38069179, 2023). "Studies have shown that the expression of CD62p and CD63 in patients with ischemic stroke was higher than in control patients on days 1, 3 and 7 following the onset of the disease." (PMID 23737893, 2013). "By using the human brain tissue sections obtained from ischemic stroke patients, we found a consistent co‐localization between FUS, CD63, and the SGs marker protein G3BP1." (PMID 38924471, 2025). "Platelet activation plays an important role in the pathophysiology of ischemic stroke; increased platelet activation markers (e.g., CD62P, CD63, and CD40L) occurred in both the acute and chronic phase after ischemic stroke." (PMID 35267542, 2022).
lung fibrosis (5 papers, 2021 to 2025). "CD9+TREM2+ macrophages expressing GPNMB, SPP1, FABP5, and CD63 were reported in murine and human pulmonary fibrosis, enriched at the edges of scars." (PMID 37756565, 2023). "Additionally, pathways such as the TIMP1/CD63/integrin β1 axis and ERK signaling have been implicated in MWCNT-induced lung fibrosis." (PMID 40423481, 2025). "However, CD9+TREM2+CD63+ SAMs expressing Spp1 present in liver and lung fibrosis were presumed to have profibrotic role across species and tissues 24-26." (PMID 38505612, 2024). "It has been identified that Timp1 stimulates fibroblasts activation and proliferation via the interaction of CD63/integrin β1, and the activation of the intracellular ERK pathway in the development of lung fibrosis." (PMID 33777519, 2021).
lymph node metastasis (5 papers, 2014 to 2025). "Notably, the elevated expression of CD63 in tumor cells is positively correlated with the risk of lymph node metastasis and poor prognosis in patients with UM." (PMID 41573746, 2025). "Furthermore, the enrichment of CD63/MDR1-double positive cells was associated with lymph node metastasis." (PMID 24884960, 2014). "In terms of cell motility regulation, CD9, CD63 and CD82 are metastasis suppressors and the expression level is inversely associated with lymph node metastasis." (PMID 34222025, 2021). "Univariate analysis revealed that the overall survival of patients was significantly correlated with CD63 expression in cancer cells, age, macroscopic type-4 cancer, undifferentiated-type cancer, tumor depth (T3-4), lymph node metastasis, distant metastasis, venous invasion, and infiltration." (PMID 30222750, 2018).
metastatic disease (5 papers, 2014 to 2024). "Using immunohistochemistry, it was shown that the increased CD63 expression was associated with a poor prognosis in CRC for a subgroup of patients with metastatic disease." (PMID 37241967, 2023). "Levels of CD63 were also associated with a poor prognosis in CRC for a subgroup of patients who presented with metastatic disease." (PMID 34830819, 2021). "The downregulation of CD63 and TSPAN32 in immune cells within metastatic tumor suggests a potential reduction in immune cell activation and responsiveness." (PMID 38255741, 2024). "CD63 overexpression was found to be an independent predictor for a negative prognosis for CRC patients at any stage, but especially for patients with metastatic disease." (PMID 37241967, 2023). "The presence of EV was confirmed on western blot by the presence of EV-enriched proteins CD9, CD63, CD81 and TSG101 in SEC fractions 7 to 10 isolated from a healthy control and a patient with metastatic disease." (PMID 37046768, 2023). "Downregulation of CD63 and TSPAN32 in immune cells within the metastatic tumor may be related to reduced immune cell activation and responsiveness." (PMID 38255741, 2024). "CD63 was found to be an independent predictor for a negative prognosis in colorectal cancer in general and also for patients with metastatic disease." (PMID 34830819, 2021).
myeloma (5 papers, 2022 to 2025). "This study elucidates a novel mechanism through which hypoxic myeloma cells transport lactate via CD63-positive exosomes, thereby remodeling the immune microenvironment." (PMID 41573746, 2025). "In this study, we developed exosome-capturing anti-CD63 mAb-conjugated small interfering RNAs (siRNAs) with branched Arg linkers and investigated their effects on multiple myeloma (MM) cells." (PMID 35158834, 2022). "Anti-CD63 mAb-conjugated complexes were incorporated into multiple myeloma (MM) cells." (PMID 35158834, 2022). "CD9 and CD63 were chosen as their median MFI was similar between healthy and myeloma EV samples and the inclusion of two EV markers would reduce the variability compared to the use of either marker alone." (PMID 36359760, 2022). "The cell and EV lysates from myeloma line RPMI 8226 was positive for CD9 but negative for CD63 and CD81." (PMID 35318648, 2022). "Given the differential expression of CD9 in EVs among the three myeloma cell lines, and the strong CD63 signal in cell lysates, we investigated whether the presence of CD9 and CD63 in EVs was correlated with their expression on the surface of the corresponding cell lines." (PMID 39126063, 2024).
ZIKV infection (5 papers, 2021 to 2024). "Furthermore, ZIKV infection was associated with the localization of CD63 to perinuclear sites in the cell, where ZIKV replication occurs." (PMID 34769038, 2021). "We also found that monocyte ZIKV infection induced tetraspanin CD63 internalization and translocation of tetraspanin CD81 and ESCRT-associated proteins TSG101 and Alix to the plasma membrane." (PMID 38247836, 2024). "Surprisingly, upon Zika virus infection, CD63 is sequestered to the core of the perinuclearly located viral replication site and surrounded by capsid protein." (PMID 34190582, 2021). "ZIKV infection alters CD63 expression levels and may utilize CD63 in the autophagic secretory pathways, contributing to the release of infectious EVs." (PMID 38396820, 2024). "In order to help visualize our hypothesis of the role of CD63 in Zika virus infection, we included a model depicting the influence of CD63 in Zika virus infection in our WT, knockdown, and overexpression cells." (PMID 34190582, 2021). "CD63 + activated neutrophils have been related to the acute phase of SARS-CoV-2 infection and to ZIKV infection protection as a marker in EVs." (PMID 38778280, 2024). "We found that CD63 is present on Mø membranes at baseline (98.7 ± 0.9%; MFI = 802.4 ± 6.2) and that during ZIKV infection, the percentage of positive cells remained stable (>90%)." (PMID 38247836, 2024). "Altogether, these results suggest that Zika virus infection and transmissive capabilities are compromised due to overexpression of CD9, CD63, and CD81." (PMID 34190582, 2021).
atherosclerosis (4 papers, 2016 to 2024). A disease characterized by the build-up of fatty material and calcium deposition in the arterial wall resulting in partial or complete occlusion of the arterial lumen. "CD63, a member of the four‐transmembrane family, is easily located in the plasma membrane from lysosome during platelet activation, and cooperates with P‐selectin to promote thrombosis in atherosclerosis." (PMID 33942972, 2021).
benign prostate hyperplasia (4 papers, 2017 to 2025). "Recently, it was shown that the CD63 concentration isolated from plasma exosomes in patients with PCa was significantly higher compared to that in patients with benign prostate hyperplasia (BPH)." (PMID 35204378, 2022). "The size and the tetraspanin content, in particular CD9, CD81, CD63 and CD41a are different in exosomes collected from benign prostatic hyperplasia, localized PC (LPC) and advanced prostate cancer (AdvPC; 58)." (PMID 34772427, 2021). "The aim of the current study was to evaluate and compare the expression of exosomal proteins CD9 and CD63 and MMR proteins in the tissue of patients with prostate benign hyperplasia (BPH) and PCa." (PMID 35204378, 2022).
cervical carcinoma (4 papers, 2014 to 2019). A carcinoma arising from either the exocervical squamous epithelium or the endocervical glandular epithelium. "In contrast, CD63 over-expression was reported to promote motility and frequency of metastases in a human uterine cervical cancer cell line, and CD63 knockdown was reported to increase invasion in vitro in esophageal carcinoma." (PMID 29523123, 2018). "Increased CAIX intensity, upregulated ZEB1 expression level, and increased number of CD63+ TAMs were strongly correlated with an advanced FIGO stage and lymph node (LN) metastasis of cervical cancer (all P < 0.05)." (PMID 31263103, 2019). "In this study, we examined the morphology of exosomes isolated from cervicovaginal lavage specimens of cervical cancer patients by electron microscopy, and measured the expression of exosome-specific markers (CD9 and CD63) by Western blot analysis." (PMID 24406730, 2014).
Cirrhosis (4 papers, 2021 to 2024). A chronic disorder of the liver in which liver tissue becomes scarred and is partially replaced by regenerative nodules and fibrotic tissue resulting in loss of liver function. "In addition to the histological inflammatory grade, there was a significant increase in mRNA expression of MCP-1, Cd112b, and CD63 in the mice that developed cirrhosis in the setting of vagotomy." (PMID 34248683, 2021). "By measuring these subpopulations (epithelial cellular adhesion molecule+ CD63+ HCC EVs, CD147+ CD63+ HCC EVs, and Glypican 3 Protein+ CD63+ HCC EVs), a logistic regression model developed an HCC EV ECG score to distinguish early-stage HCC from cirrhosis." (PMID 39451600, 2024).
depression (4 papers, 2022 to 2025). "In the present study, the KOA patients with elevated CD41+/CD63+/CD9+ sEVs reported greater BDI scores, supporting the known association between platelet activation and depression." (PMID 38254142, 2024). "In the search of an explanatory model for the observed associations between depression and the blood levels of PPP3R1, CD63, and ASGR1, platelets emerge as potentially pivotal players." (PMID 38812487, 2024). "Another study also demonstrated increased CD63 expression in platelets from patients with depression, suggesting that alterations in CD63 expression could be pivotal in platelet hyperactivation among depressed individuals." (PMID 40370590, 2025). "Other interesting findings involve two proteins, ASGR1 and CD63, corresponding to genes that may offer new insights into the pathophysiological processes of depression." (PMID 38812487, 2024). "In this study, functional enrichment analysis revealed that targets such as CD63, IL17RA, and IL1R1 are involved in depression-related pathways, including the HIF-1, MAPK, and PI3K-Akt signaling pathways." (PMID 40370590, 2025). "In this study, CD63 expression was significantly upregulated in patients with MDD, aligning with existing evidence that CD63 exacerbates the pathological course of depression." (PMID 40370590, 2025). "Although several potential drugs targeting CD63, IL17RA, and IL1R1 were identified, limited research exists on their effects on MDD or depression." (PMID 40370590, 2025). "The observed connection between depression and CD41+/CD63+/CD9+ sEVs in KOA suggests that the potential of EV subpopulations as biomarkers of mental status warrants further investigation." (PMID 38254142, 2024).
Down syndrome (4 papers, 2020 to 2024). "In addition, enhanced secretion of CD63 and Rab35-containing EVs were associated with neurological disorder such as Down syndrome which was suggested as a mean for the cells to alleviate endosomal pathology through EVs secretion." (PMID 32466345, 2020). "CD63 induces the biogenesis of EVs, whereas CD63 expression facilitates the release of EVs in Down syndrome." (PMID 37676390, 2024). "In addition, enhanced exosome secretion and increased CD63 levels have been reported in the brains of Down syndrome patients." (PMID 36611951, 2022). "Higher levels of CD63 expression have also been found in the brain of Down syndrome patients and a mouse model of the disease, and as in the present study, are associated with a higher amount of multivesicular bodies and with higher levels of exosomes in the extracellular space." (PMID 33741962, 2021).
gastrointestinal stromal tumor (4 papers, 2021 to 2023). "For instance, poor outcomes for patients with GIST (gastrointestinal stromal tumors) are associated with overexpressed CD63 and GLUT-1, which are markers of hypoxic state." (PMID 37289328, 2023). "Increased CD63 expression was associated with poor prognosis in patients with gastrointestinal stromal tumors." (PMID 34316329, 2021). "For example, overexpressed CD63 and GLUT-1 are markers of hypoxia status and are associated with poor outcomes of GIST (gastrointestinal stromal tumors) patients." (PMID 35039054, 2022).
neuroblastoma (4 papers, 2020 to 2024). Neuroblastoma (NB) is the most common solid, extracranial childhood tumor. "From this perspective, we conducted another CIBER screening with the DTKP library (2333 genes with 24,569 gRNAs, drug targets, kinases, and phosphatases) in SH-SY5Y cells (derived from human neuroblastoma) expressing CD63-dCas9." (PMID 39562573, 2024). "We detected vesicles of sizes similar to those detected in the supernatant of neuroblastoma cells, which were positive to the CD63 marker." (PMID 34847775, 2021). "Using confocal imaging, we confirmed that LGALS3BP co-localizes with the exosome markers CD-63 and CD-81 and its mature form is enriched in exosomes/EVs isolated from SKNAS but not hNB neuroblastoma cells, providing an opportunity for specific targeting with 1959 antibody." (PMID 33076448, 2020).
pancreatic ductal adenocarcinoma (4 papers, 2022 to 2024). An infiltrating adenocarcinoma that arises from the epithelial cells of the pancreas. "Additionally, Odaka and colleagues found that serum levels of CD63-positive EVs were significantly higher in pancreatic ductal adenocarcinoma patients compared to healthy controls." (PMID 38568288, 2024).
thalassemia (4 papers, 2011 to 2025). An inherited blood disorder characterized by a decreased synthesis of one of the polypeptide chains that form hemoglobin. "It was found that the expression levels of platelet activation markers (CD62P and CD63) were significantly upregulated in patients with thalassemia." (PMID 37362622, 2023). "In thalassemia, increased platelet activation and aggregation have been well documented, alongside elevated levels of platelets expressing activation markers such as CD62P (P-selectin) and CD63." (PMID 39859141, 2025).
thrombosis (4 papers, 2013 to 2021). "Panax notoginseng can reduce the levels of CD62p, CD63, GPIIb/IIIa, FIB, and D-dimer in plasma of patients with deep venous thrombosis and thus play a therapeutic role." (PMID 33880123, 2021). "Of note, the expression of tetraspanins, namely CD81, CD63, and CD9, and the number/size of the isolated EVs were not significantly different between PV patients with or without thrombosis history (data not shown)." (PMID 34638452, 2021).
type 2 diabetes (4 papers, 2016 to 2025). "Increased expression of platelet activation markers CD31, CD36, CD49b, CD62P and CD63 was confirmed by Eibl and co-workers when type 2 diabetics were compared with normal individuals." (PMID 27036108, 2016).
astrocytoma (3 papers, 2018 to 2020). "The aim of this study was to assess CD63 expression in astrocytomas focusing on the prognostic potential of CD63 alone and in combination with TIMP-1." (PMID 29523123, 2018). "The association between CD63 and TIMP-1 was investigated using previously obtained TIMP-1 data from our astrocytoma cohort." (PMID 29523123, 2018). "CD63 expression was investigated immunohistochemically in a cohort of 111 astrocytomas and correlated to tumor grade and overall survival by semi-quantitative scoring." (PMID 29523123, 2018). "To further examine the impact of CD63 in astrocytomas, we used TCGA datasets." (PMID 29523123, 2018). "The aim of this study was to assess the prognostic impact of CD63 alone and in combination with TIMP-1 by performing immunohistochemistry on a cohort of 111 astrocytomas, described and used previously for evaluation of the prognostic potential of TIMP-1." (PMID 29523123, 2018).
Autoimmunity (3 papers, 2016 to 2022). The occurrence of an immune reaction against the organism's own cells or tissues. "When ASST‐/CD63‐ a 30.50% of patients required also third line of treatment suggesting other mechanisms involved in the development of the wheals than those involved in autoimmunity." (PMID 27980778, 2016).
breast adenocarcinoma (3 papers, 2018 to 2024). "The design was validated by biofunctionalizing the nanosensors with anti-CD63 antibodies targeted towards the tetraspanin CD63 membrane bound proteins present in exosomes secreted by MCF7 breast adenocarcinoma cells." (PMID 30142169, 2018). "Therefore, to target the tetraspanins CD63 membrane-bound proteins in exosomes secreted by MCF7 breast adenocarcinoma cells, the plasmonic nanopillars were functionalized with anti-CD63 antibodies." (PMID 35630197, 2022).